GSK3B (glycogen synthase kinase 3 beta)
Diseases named in the same sentence as GSK3B in open-access papers (continued):
Sharing a sentence is not in itself a finding about the gene and the disease.
cancer (continued). "Therefore, combination of TRAIL and chemotherapeutic drugs may be a good strategy for treatment of cancer with multidrug resistance, and DNA-PKcs/Akt/GSK-3β signaling pathway may be an important target to overcome multidrug resistance." (PMID 20663232, 2010). "Importantly, the pro-survival GSK3β-dependent pathway may represent a new therapeutic target in cancer cells whose resistance to therapy is supported by cell adhesion." (PMID 20352103, 2010). "Thus, the biological significance of GSK-3β in each cancer type needs to be elucidated." (PMID 20704706, 2010). "While the use of GSK3β specific inhibitors has not been linked to the development of cancer, our observations provide further evidence for the potential of these compounds to interact negatively with anti-cancer therapeutics." (PMID 17018141, 2006). "This study provides a comprehensive pan-cancer atlas of GSK3 isoform-specific functionality, nominating GSK3β as a high-priority therapeutic target." (PMID 41915675, 2026). "Lithium salts are known to inhibit glycogen synthase kinase-3 beta (GSK-3β), a protein that plays a crucial role in tumorigenesis in various cancers." (PMID 41590345, 2026). "Among these shared targets, several key genes involved in cancer-related pathways were identified, including EGFR, PARP1, SRC, MET, GSK3B, and CYP19A1." (PMID 40963691, 2025). "Akt upregulates this pathway by phosphorylating and inhibiting GSK3β, leading to several traits that promote cancer progression, such as decreased E-cadherin expression (a typical EMT marker), cancer cell detachment, and metastasis." (PMID 40362591, 2025). "We found that the Akt–GSK3β axis can be regulated by TRAF6, which is consistent with the literature on the role of Pim1 in cancer." (PMID 40164682, 2025). "In summary, our findings suggest that one of the cancer-promoting effects of NAT10 is to promote the expression of NFE2L3, form the NAT10-NFE2L3-LASP1-Akt/GSK3β axis, and promote the occurrence and progression of ccRCC." (PMID 40169553, 2025). "While the functions and mechanisms of GSK3β are well-documented, its specific role in TBX21-mediated cancer metastasis remains unexamined." (PMID 39744435, 2025). "Pharmaceutical compounds that target essential components of the circadian clock, such as GSK-3β inhibitors, CRY stabilizers, CRY inhibitors, CK1 inhibitors, CK2 inhibitors, and REV-ERB agonists, are being developed and show anti-cancer potential." (PMID 40040723, 2025). "It accomplishes this by downregulating essential molecules involved in various signaling pathways that favor cancer cell survival and proliferation, EGF and its receptor EGFR, along with key downstream effectors such as PKB and GSK-3β." (PMID 40656954, 2025). "Pharmacological inhibition of Akt signaling leads to YAP degradation in a GSK-3β/FBXO9-dependent manner, significantly enhancing chemosensitivity in cancer models." (PMID 40902979, 2025). "Overall, compared to those of LSEC and LSCC, DR‐LSCC showed upregulated expression of microtubule stabilization genes like ALK gene, metabolic gene GSK3B, and a slight increase of hypoxia gene HIF1A in the KEGG hsa05200 cancer pathway." (PMID 40385549, 2025). "The authors of the study proposed a mechanism by which PD-L1 binding to PTPB1B prevented GSK3β-mediated phosphorylation and subsequent degradation by ubiquitination of Snail, promoting epithelial to mesenchymal transition (EMT) in cancer cells." (PMID 40427133, 2025). "From a molecular mechanism perspective, ginkgetin exerts anti-cancer activity by modulating critical signaling pathways (e.g. JAK/STAT, Wnt/β-catenin, AKT/GSK-3β, MAPKs, and estrogen receptor pathways) and regulating microRNA expression levels." (PMID 40762894, 2025).
cancer (continued). "PP2A is a potent protein phosphatase that contains the C catalytic subunit PP2Ac, which dephosphorylate pS62-c-Myc, p-GSK3β, p-ERK and p-AKTT308 in cancer cells." (PMID 40860184, 2025). "The dysregulation of MUC15 is observed in many cancers with links to EMT via EGFR inhibition, PI3K-Akt, and GSK3β/β-catenin signaling." (PMID 39483899, 2024). "There is mixed evidence about the role of PIGR in cancer, but some evidence suggests that PIGR promotes oncogenic AKT activity with downstream effects on GSK3B/β-catenin that are reversed by AKT inhibition." (PMID 38954770, 2024). "(b) ATO and APA inhibit cancer progression via modulation of VEGFR2/Akt/mTOR and Akt/GSK-3β/c-Myc signaling pathway." (PMID 39223679, 2024). "In actively proliferative OSCC tumors, cancer cells exhibit high levels of p-AKT, p-Rb, and p-GSK3β." (PMID 38755637, 2024). "A few reports mention that phosphorylation of this transcriptional factor regulates positively and negatively in cancer, due to transactivation domain and the presence of PKA, GSK3β, and βTrCP." (PMID 38370352, 2024). "Glycogen synthase kinase-3 beta (GSK-3β) is a serine/threonine kinase that has been extensively researched for its involvement in different physiological conditions, especially cancer." (PMID 38800305, 2024). "In cancers, NUP58 regulates the glycogen synthase kinase 3 beta/zinc finger protein Snai1 (GSK-3β/Snail) signaling pathway and bipolar spindle formation, thereby exerting its carcinogenic effect." (PMID 39080077, 2024). "The phosphorylation of downstream targets, including GSK3β, has been proposed as a major player in AKT-induced cancer cell survival." (PMID 39339236, 2024). "It has been reported that CDK1 promotes cancer cell migration and metastasis by phosphorylating proteins such as EZH2 and activating pathways such as Wnt/β‐Catenin and the ERK/GSK3β/SNAI axis." (PMID 38842135, 2024). "Recent studies have shown that GSK-3β upregulates the expression of inhibitory receptors LAG-3 and PD-1 in T cells, highlighting its potential as a therapeutic target in cancer immunotherapy." (PMID 39340067, 2024). "Our work presents CerS6 and specifically CerS6 glycosylation, as a potential therapeutic target for the modulation of GSK3β and AKT signaling in cancer models." (PMID 39608570, 2024). "In cancer, curcumin’s effectiveness is determined by examining its interaction with pivotal proteins like CDK2, CK2α, GSK3β, DYRK2, and EGFR, among others." (PMID 38474160, 2024). "Previous studies have shown that the AKT/GSK3β/c-Fos/NFATc1, IGF-1/AKT/NF-κB (RelA) or TGF-β/Smad3/4 signaling cascade play a key regulatory role in BMM of many cancers." (PMID 37337244, 2023). "Several studies reported that some AURKA substrates, including GSK3β and β-catenin, participated in crucial oncogenic signaling, and AURKA directly phosphorylated GSK3β in cancer cells, which stabilized β-catenin and activated Wnt signaling." (PMID 36937887, 2023). "Several other studies have also shown that c-Met expression enhances the Wnt/β-catenin signaling and impedes GSK3β from phosphorylating β-catenin in CRC; this subsequently promotes β-catenin translocation into the nucleus leading to cancer initiation." (PMID 36672275, 2023). "Of all the cancer cell lines used, GBM8401 and U87MG demonstrated the highest expression level of both galectin-3 and GSK3B." (PMID 37185758, 2023). "The literature indicates that GSK-3β inhibitors can reduce tau phosphorylation and tau toxicity, and that GSK-3β inhibition is a potential strategy for treating cancer." (PMID 37108703, 2023). "The anti-cancer effect of niclosamide was mediated by the downregulation of the Wnt/β-catenin signaling, which downregulated β-catenin, Cyclin D1, DVL2, and p-GSK3β proteins in the ALDH+ treated cells." (PMID 38170015, 2023). "Our results showed that majority hub genes DCAF7, FGF2, GSK3B, NACC2, and NFIB were highly expressed and (nTPM >19) localised mainly in the nuclei of the cancer cells." (PMID 36468011, 2022).
cancer (continued). "Glycogen synthase kinase 3 beta (GSK-3β) enables successive phosphorylation of the Snail protein to control its abundance, further monitoring EMT in cancer cells." (PMID 35805066, 2022). "The ongoing trials using GSK-3β inhibitors for treating PDAC and other cancers will reveal more data about this treatment strategy." (PMID 36430630, 2022). "In contradiction with this data, GSK-3β inhibitors such as BIO, TWS119, and LiCl, decreased the expression of mesenchymal markers in different cancer cell lines with a mesenchymal phenotype." (PMID 36430630, 2022). "A total of five cancer-related genes (BDNF, PTGS2, CTNNB1, GSK3B, and HPGD) were selected based on the Gene Ontology database." (PMID 35054980, 2022). "Subsequently, IL1-β secreted by TAMs stabilizes intracellular β-catenin potentiating Wnt signaling in cancer cells via NFkB/PDK1 and glycogen synthase kinase 3-beta (GSK3β) inhibition, whereas IL-6 further amplifies inflammation within the TME." (PMID 36613445, 2022). "This drug (SB-216763) inhibited Glycogen synthase kinase-3 beta (GSK-3), which is known to be a therapeutic target for numerous human diseases, including cancer." (PMID 36009461, 2022). "They inhibited the proliferation and metastasis of cancer cells by downregulating the PI3K/AkT signaling cascade and reducing cyclin D1 levels via the activation of GSK-3β." (PMID 35807651, 2022). "Recently, PIK3CD has been reported to be associated with the homeostasis and function of B and T cells, and can induce cancer cell growth and invasion by activating AKT/GSK-3β/β-catenin signaling in CRC." (PMID 36246627, 2022). "Focus is usually directed at examining the function of central components of the WNT pathway, including β-CATENIN and the GSK3β complex and TCF/LEF transcription factors, in tissue homeostasis and cancer." (PMID 35589804, 2022). "This pathway is activated by Wnt/GSK-3β independently of β-catenin and is considered another anti-oncogenic effect of GSK-3β in PDAC as mTOR is a major pro-cancer effector in PDAC." (PMID 36430630, 2022). "The GSK3B, a central component of PI3K/Akt survival pathway, determines the cancer cell survival through its effects on apoptosis." (PMID 36468011, 2022). "In the current study, we proposed that GSK‐3β inhibition by TDZD‐8 reduced Drp1 mediated mitochondrial fission to decrease inflammation reaction and relieve cancer induced bone pain." (PMID 35689386, 2022). "Taken together, GSK‐3β inhibition by TDZD‐8 decreases spinal inflammation and relieves cancer induced bone pain via reducing Drp1‐mediated mitochondrial damage." (PMID 35689386, 2022). "Through the PI3K/Akt signaling pathway and the Akt/GSK3β/β-catenin pathway, UBE2T is involved in the cell proliferation, migration, and invasion of cancer cells." (PMID 35035504, 2022). "Taken together, our findings elaborate an indispensable role of GSK-3β in determining ferroptotic sensitivity by dominating cellular iron metabolism, which provides further insight into GSK-3β as a target for cancer chemotherapy." (PMID 34732689, 2021). "CRKL up‐regulation potentially promotes hepatocarcinogenesis via enhancing cancer cells’ glucose metabolism through increasing GLUT1 expression, potentiating HKII activity and inactivating GSK3β activity." (PMID 33523562, 2021). "Studies reported that CXCL5 induced the EMT process in cancer cells by activating ERK/Elk-1/Snail, AKT/GSK3β/β-catenin, or ERK/Snail signaling pathways." (PMID 34603292, 2021). "Based on the totality of our findings, we propose the following model: CCL16 (a potential cancer stemness gene) binds to the CCR2 receptor and activates p-AKT/GSK3β signaling, which enhances β-catenin stability and promotes β-catenin nuclear translocation." (PMID 33500726, 2021).
cancer (continued). "To further investigate the effect of GSK-3β on ferroptosis, we established two stable GSK-3β KD cancer cell lines (HeLa and MDA-MB-231) by using two specific short hairpin RNAs (shRNAs) (referred to as GSK-3β KD 1# and 2#)." (PMID 34732689, 2021). "Under normal conditions, cancer cells turn on the canonical Wnt/β-catenin pathway to disintegrate the destruction complex (Axin, APC, GSK3β, and β-catenin; dash circle) and stabilize β-catenin." (PMID 34069945, 2021). "Other studies have shown that ARRB1 regulates several cancer-related cellular processes via diverse signal transduction pathways, including the Ras/Raf/MEK/ERK family, β-catenin/TCF4 signalling, Akt/GSK3β signalling, mTOR signalling and NF-κB signalling." (PMID 34380537, 2021). "The AKT/GSK-3β/β-catenin pathway is the “crosstalk” between the PI3K/AKT and Wnt/β-catenin pathways, which is one of the most studied pathways in cancer development." (PMID 33777320, 2021). "GSK-3β-regulated MMP expression, for example, was involved in SLFN5-controlled inhibition of cancer cell migration and invasion." (PMID 35095838, 2021). "In cancer, previous studies indicated that Akt activation can trigger EMT by phosphorylating and thereby inhibiting GSK3β, preventing it from phosphorylating Snail and thus preventing Snail nuclear export and degradation." (PMID 34168980, 2021). "6-shogaol significantly reduced the expressions of p-PI3K, p-AKT, and p-mTOR in OSCC cells; and also inhibited GSK3β downstream of AKT, which plays an important role in the proliferation and apoptosis of cancer cells." (PMID 34644781, 2021). "To confirm the role of GSK3β in promoting MMP-9 expression, we examined its induction in cancer cells co-transfected with the ETS1 expression vector and GSK3β siRNA." (PMID 34023818, 2021). "KRT19, FKBP10, GSK3B, and SPANXB1 have been investigated at the single-cell level in 9, 10, 16 and 3 types of cancer, respectively." (PMID 35096583, 2021). "Key cancer-related pathways and proteins that these genes can regulate include the AKT/GSK-3β/SNAIL pathway, MMP-9, CD44 and STMN1 which are involved in EMT and metastasis." (PMID 33374923, 2020). "It is possible that the effect of melatonin in normal cells involves activation of the PI3K/AKT pathway and therefore inactivation of GSK-3β in contrast to the observed effect in the SK-MEL-1 and other cancer cells." (PMID 32674468, 2020). "The results indicated that GSK-3β induced PTEN phosphorylation and led to AKT activation in cancer cells." (PMID 32973135, 2020). "Then the release of β-catenin from the plasma membrane and further activation of the Wnt signaling pathway (phosphorylation/degradation of GSK3β and decomposition of the APC/Axin/GSK3β complex) occur, leading to enhanced EMT and invasion of cancer cells." (PMID 33520714, 2020). "Target prediction analysis showed that miR-186-5p potentially targets Gsk3b, which is involved in many pathways such as the PI3K-akt signaling pathway, ErbB signaling pathway, pathways in cancer, and insulin signaling pathway." (PMID 33133155, 2020). "Of note, positive correlations of ASPH with GSK3B and CTNNB1 have been found in the normal tissues, cancer tissues as well as cancer cell lines." (PMID 33015050, 2020). "Extensive genes have been identified as the target of miR-761 in numerous cancers, including HDAC1, Rab3D, Runx3, Mitofusin-2, CXCR1, TRIM29, MSI1, ING4, TIMP2, and GSK3β." (PMID 32185226, 2020). "Taken together, these results suggest that DEX inhibits TRAIL-mediated apoptosis via GSK-3β-mediated DR5 downregulation and c-FLIP(L) upregulation in cancer cells." (PMID 33050333, 2020).
cancer (continued). "MiR‐500a‐3p has been reported to be involved in the chemoresistance, invasion and migration via GSK‐3β and LY6K in different types of cancers." (PMID 32588541, 2020). "Snail, an important transcription factor in embryonic development and cancer progression, is controlled by the AKT/GSK-3β pathway, which was also inactivated after the knockdown of G6PD." (PMID 32719549, 2020). "Agreement with our results, GSK-3β was higher and RARβ lower in HCC than adjacent liver tissue, which phenomenon was also observed in many other malignant tumors." (PMID 31938062, 2020). "In bone-related cancer cell lines, ASPH has significant correlations with GSK3B (Pearson r = 0.50, p = 0.01) and CTNNB1 (Pearson r = 0.54, p = 0)." (PMID 33015050, 2020). "Collectively, our data supports an essential contribution of GSK3β-Fbxw7α to the tightly regulated turnover of IRF1 protein during the transcriptional cycle and, thus its anti-cancer activities." (PMID 30854564, 2019). "AKT/GSK3β/β-catenin, ERα, and JNK/p38 signalling play important roles in the inhibition of proliferation and metastasis of human cancer cells by Huaier28,30,34." (PMID 30679589, 2019). "The phosphorylation of GSK-3β by AKT mediates abnormal expression of β-catenin and β-catenin has impact on the transactivation of AR to drive the progression in cancer." (PMID 31126320, 2019). "A panel of eight cancer driver genes (CCNE1, TPX2, ELF3, FANCL, JAK2, GSK3B, CEP76, and SYK) were differentially expressed in recurrent TNBCs, and were also overexpressed in TCGA and METABRIC." (PMID 30665374, 2019). "On the other hand, GSK3β also modulates CSC stemness and cancer cell migration through Wnt-independent mechanisms, such as regulation of histone methylation and other feedback signaling." (PMID 30275459, 2018). "The augmentation of Wnt/β-catenin signalling through Ser9 phosphorylation-inactivation of GSK3β is a well-recognised regulatory pathway for CSC self-renewal and cancer development." (PMID 29940988, 2018). "In our study, we found that IGF-1 stimulated the phosphorylation of GSK-3β in PC12 cells, indicating that the inhibition of GSK-3β plays a positive role in promoting the development of cancer, at least in IGF-1R-mediated cancer." (PMID 30213025, 2018). "These kinases include CDK, GSK-3β, CK1 and cyclic nucleotide-dependent kinases, which are important in cancer and neurodegenerative disease." (PMID 29757250, 2018). "Although KRT19 regulates EGR1/PTEN/AKT, β-catenin/NUMB/NOTCH, and HER2/ERK/SP1 cascades, we focused on the AKT, GSK3β, ERK, Src, and JNK signaling pathway in this study, as these signaling pathways are crucially involved in cancer progression." (PMID 29747452, 2018). "Constitutively phosphorylated AKT has been reported in some cancers, and activated AKT promotes cell proliferation and induces apoptosis via phosphorylating a number of transcription factors including GSK3β." (PMID 28407749, 2017). "The change in the phosphorylation status of GSK3β or p38MAPK was confirmed in both CST1 knockdown MDA-MB-231 and SW480 cancer cells." (PMID 28383558, 2017). "The ALK/GSK3β/β-catenin pathway is an impor-tant PTN-induced pathway that is involved in neural development and cancer progression." (PMID 28969035, 2017). "SPHK-1 activates the AKT/GSK-3β signaling pathway, which is involved in the accumulation of HIF-1α levels under hypoxia in cancer." (PMID 28165392, 2017). "Functional cell-based experiments demonstrated direct interaction between miRNA-26a and GSK-3β; in addition, miRNA-26a-mediated reduction of GSK-3β resulted in activation of β-Catenin and expression of cancer-driving genes such as cell cycle promoters." (PMID 27957497, 2016). "Recent work demonstrated that GSK-3β is involved in the process of tumorigenesis by participating in the NF-κB-mediated gene transcription, which predicts that GSK-3β would promote cancer cell proliferation." (PMID 26575170, 2016).